USP36 (ubiquitin specific peptidase 36)
Diseases named in the same sentence as USP36 in open-access papers (continued):
Sharing a sentence is not in itself a finding about the gene and the disease.
colon carcinoma (5 papers, 2016 to 2026). "Our data demonstrated that CBF significantly suppressed proliferation, stemness, invasion, as well as migration of colon cancer cells and sensitizes these cells to Oxa-induced cytotoxicity, whereas enforced expression of USP36 partly blocked these effects." (PMID 38517383, 2024). "Bioinformatics analyses indicated that USP36 is highly expressed and significantly related to tumor stages in colon cancer." (PMID 38517383, 2024). "Our research provides multiple lines of evidence for the oncogenic role of USP36 in colon cancer cells." (PMID 38517383, 2024). "In our present study, we found an up-regulation of USP36 in colon cancer based on the bioinformatic database-GEPIA." (PMID 38517383, 2024). "Based on the analysis from GEPIA, the expression of USP36 in colon cancer samples was significantly higher than that in the normal, and was closely related to the tumor stage." (PMID 38517383, 2024). "Nevertheless, few reports have shown the relationship between USP36 and the aggressive phenotypes of colon cancer." (PMID 38517383, 2024). "Compared with NCM460 cells, USP36 was highly expressed in all colon cancer cell lines and further up-regulated in Oxa-resistant colon cancer cells." (PMID 38517383, 2024). "Herein, we aimed to determine the role and mechanism of USP36 in malignant phenotypes of colon cancer cells and explore the potential drug targeting USP36." (PMID 38517383, 2024). "Collectively, a series of functional experiments revealed the oncogenic effect of USP36 on colon cancer cells in vitro." (PMID 38517383, 2024). "Based on the bioinformatics online database, USP36 was shown a more significant up-regulation in colon cancer than that in normal samples." (PMID 38517383, 2024). "To conclude, this research demonstrated through extensive in vitro and in vivo studies that USP36 is an oncogene in colon cancer through targeting c-Myc and uncovered CBF as a promising therapeutic agent for colon cancer." (PMID 38517383, 2024). "In summary, our research demonstrated that USP36 promotes the aggressiveness, chemoresistance, and metastasis of colon cancer by deubiquitinating and stabilizing c-Myc, and uncovered a potential USP36 inhibitor, CBF, in the treatment of colon cancer." (PMID 38517383, 2024). "In vitro experiments indicated that the proliferation, migration, stemness, and invasion of colon cancer cells were all promoted after overexpressing USP36, while were impaired by silencing USP36." (PMID 38517383, 2024). "In conclusion, CBF may be a promising therapeutic agent for colon cancer due to its regulation of the USP36/c-Myc axis." (PMID 38517383, 2024). "Next, the oncogenic role of USP36 in colon cancer was validated by in vivo animal studies." (PMID 38517383, 2024). "However, the role and mechanisms behind the abnormal expression of USP36 in colon cancer remain elusive." (PMID 38517383, 2024). "Hence, the interaction between USP36 and c-Myc in colon cancer cells was investigated to uncover the potential mechanism underlying the oncogenic effect of USP36." (PMID 38517383, 2024). "Hence, our present study attempts to determine the role of USP36 in malignant phenotypes of colon cancer cells and uncover the function mechanism and further explored potential therapeutic drugs targeting USP36 for patients with colon cancer." (PMID 38517383, 2024). "Due to its oncogenic function in colon cancer, the USP36/c-Myc axis may be a potential target for developing the anticancer drug." (PMID 38517383, 2024). "Moreover, in vivo studies further validated the oncogenic role of USP36 in colon cancer." (PMID 38517383, 2024). "Therefore, it could suppose that USP36 contributes to the stabilization of the c-Myc protein in colon cancer cells via deubiquitination, which may be the mechanism behind the promotive function of USP36 on the aggressive phenotypes of colon cancer cells." (PMID 38517383, 2024).
colon carcinoma (continued). "Besides, USP36 was further up-regulated in oxaliplatin (Oxa)-resistant colon cancer cells." (PMID 38517383, 2024). "Given the oncogenic activity of USP36 has been demonstrated in various malignancies, we wonder whether USP36 is related to the aggressiveness, chemoresistance, and metastasis of colon cancer and could be a promising target of colon cancer management for improving prognosis." (PMID 38517383, 2024). "USP32, USP1, USP37, USP12, and USP6 are elevated in macrophages, while USP32, USP9X, USP46, USP12, USP36, and USP24 are upregulated in classical monocytes of colon cancer relative to the control group." (PMID 41356798, 2026). "Our data also indicated that USP36 contributed to the Oxa resistance to colon cancer cells, as indicated by the IC50 value of HCT116 cells to Oxa was significantly changed after the transfection of USP36 OE or sh-USP36." (PMID 38517383, 2024). "Ubiquitin-specific protease 36 (USP36) has been reported to exhibit oncogenic effects in various malignancies, but the function of USP36 in colon cancer progression remains indefinite." (PMID 38517383, 2024). "Moreover, in vivo analyses confirmed the oncogenic role of USP36 and the therapeutic potential of CBF in the malignancy of colon cancer." (PMID 38517383, 2024). "In addition, the expression level of USP36 was monitored between NCM460 (the normal human colon mucosal epithelial cells) and colon cancer cells (SW480, HCT116, Lovo, and CaCO2), and between Oxa-resistant cell lines and the parental one." (PMID 38517383, 2024). "c-Myc-dependent tumors (adenocarcinomas and non-small lung, breast, and colon cancer) could potentially respond to USP28, USP36, USP37, all DUBs affecting c-Myc protein turnover." (PMID 27516771, 2016).
lung carcinoma (3 papers, 2021 to 2026). "Multiplex RT-PCR showed distinct mRNA expression profiles of several DUB genes, including USP35, USP36, USP37, USP47, USP49, and OTUD6B in A549 lung cancer cells following exposure to cisplatin." (PMID 41399373, 2026). "Following the observation of altered expression levels of USP35, USP36, USP37, USP47, USP49, and OTUD6B in response to cisplatin treatment in lung cancer cells, both at the mRNA and protein levels, we sought to explore their significance in lung cancer." (PMID 41399373, 2026). "USP36 and USP37 have been reported to regulate tumorigenesis by preventing MYC degradation in breast and lung cancer [16,35,]." (PMID 34272356, 2021). "Substantiating these findings, western blotting analysis confirmed the protein expression levels of USP35, USP36, USP37, USP47, USP49, and OTUD6B in cisplatin-treated lung cancer cells, mirroring the mRNA trends observed in non-treated counterparts except for OTUD6B." (PMID 41399373, 2026).
cardiomyopathy (2 papers, 2024 to 2025). A disease of the heart muscle or myocardium proper. "The association between USP36 and cardiomyopathy is predominantly manifested in its function in doxorubicin (Dox)-induced cardiomyopathy (DIC)." (PMID 38785979, 2024). "This investigation provides compelling evidence that USP36 deubiquitinates PARP1, suggesting that the USP36/PARP1 axis is a promising therapeutic target for Dox-induced cardiomyopathy." (PMID 38785979, 2024). "USP36 has been implicated in a range of non-cancerous conditions, including AKI, nonalcoholic steatohepatitis, human papillomavirus infection, and cardiomyopathy." (PMID 38785979, 2024).
colorectal cancer (2 papers, 2020 to 2024). A primary or metastatic malignant neoplasm that affects the colon or rectum. "Although USP39 functions have been extensively studied, the role of USP36 in colorectal carcinoma remains ambiguous." (PMID 38876304, 2024). "USP36 protein expression was higher in colorectal carcinoma cell lines than in the control cell line, with the highest expression detected in HCT-8, HCT 116, and RCM-1 cell lines." (PMID 38876304, 2024). "The protein expression of USP36 was measured in six different colorectal carcinoma cell lines and the control human normal colon epithelial cell line (NCM 460)." (PMID 38876304, 2024).
diabetes (2 papers, 2016 to 2021). "Additionally, we identified several genes with cASE that have been associated with diabetes (GIPC1, USP36, RNF213, KCTD12) or obesity (PIP5K1A) (78, 79, 81, –, 83)." (PMID 27709125, 2016). "Nevertheless, the role of USP36 in diabetes has never been reported yet." (PMID 33968925, 2021).
diabetic kidney disease (2 papers, 2021 to 2023). Progressive kidney disorder caused by vascular damage to the glomerular capillaries, in patients with diabetes mellitus. "Taken together, our have found that USP36-mediated deubiquitination of DOCK4 contributes to the diabetic kidney disease via the Wnt/β-catenin signaling pathway." (PMID 33968925, 2021). "In brief, USP36-mediated deubiquitination of DOCK4 could contribute to the EMT in diabetic kidney disease via the Wnt/β-catenin signaling pathway." (PMID 33968925, 2021). "Similarly, independent studies identified USP36 in renal epithelial cells, and USP14, 15, and 22 in podocytes as complicating factors for diabetic nephropathy; however, the contribution of each USP to disease etiology is still unclear." (PMID 36834633, 2023).
esophageal squamous cell carcinoma (2 papers, 2024 to 2025). Esophageal squamous cell carcinoma (ESCC) is a type of esophageal carcinoma (EC) that can affect any part of the esophagus, but is usually located in the upper or middle third. "The findings of the current study highlight the significance of USP36 in the modulation of Hippo signaling activity and growth of esophageal squamous cell carcinoma (ESCC)." (PMID 38785979, 2024).
gastric cancer (2 papers, 2022 to 2023). A primary or metastatic malignant neoplasm involving the stomach. "In contrast, USP36 repressed Hippo signaling by regulating TAZ protein ubiquitination levels in gastric cancer." (PMID 37041150, 2023).
glioma (2 papers, 2021 to 2024). A benign or malignant brain and spinal cord tumor that arises from glial cells (astrocytes, oligodendrocytes, ependymal cells). "The clinical significance of the USP36-ALKBH5 pathway was assessed by investigating the expression of the USP36 protein in both normal human brain tissues and gliomas." (PMID 38398118, 2024). "In gliomas, the levels of USP36 protein were found to be elevated compared to normal brain tissues, and this elevation exhibited a positive correlation with the malignant grade of gliomas." (PMID 38398118, 2024). "Importantly, the expression levels of ALKBH5 and USP36 protein correlated with each other in the human gliomas." (PMID 38398118, 2024). "We tested five DUBs in glioma cells that may be involved in regulating Snail2 degradation, of which only USP36 was affected by PRL1 overexpression or knockdown." (PMID 35111679, 2021).
Nephropathy (2 papers, 2024 to 2025). A nonspecific term referring to disease or damage of the kidneys. "USP36 deubiquitinates DOCK4 (a mono-ubiquitinated protein), which promotes Wnt/β catenin signaling, diabetic tubular renal injury, and consequently nephropathy." (PMID 41007744, 2025).
asthenozoospermia (1 paper, 2020). "Subsequent Sanger sequencing on genomic DNA from all the available family members (III:1, III:2, and IV:1–7) verified four variants in four genes (DNAH17, GPS1, HID1, and USP36) recessively coinherited with asthenozoospermia." (PMID 31658987, 2020).
atrial fibrillation (1 paper, 2025). A disorder characterized by an electrocardiographic finding of a supraventricular arrhythmia characterized by the replacement of consistent P waves by rapid oscillations or fibrillatory waves that vary in size, shape and timing and are accompanied by an irregular ventricular response. "For the hypertension and atrial fibrillation pairing, signals implicating shared causal variants were seen on chromosomes 4, 7, 11, and 17, in the genes FGF5, HOXA13, in the region spanning LSP1 to TNNT3 and that spanning CYTH1 to USP36 respectively." (PMID 40538118, 2025).
breast tumor (1 paper, 2024). "Furthermore, In the xenograft mice model, depleting USP36 hindered breast tumor growth and boosted tamoxifen’s inhibitory effect in the Y537S-expressing MCF-7 model." (PMID 39215346, 2024).
colorectal tumor (1 paper, 2024). "Additionally, USP36 expression levels increased in colorectal tumor samples at all stages." (PMID 38876304, 2024).
esophageal cancer (1 paper, 2022). A primary or metastatic malignant neoplasm involving the esophagus. "We found that USP36 expression was elevated in human esophageal cancer and positively correlated with YAP protein levels in human samples." (PMID 36470870, 2022). "The public available TCGA data implicated that USP36 expression was conspicuously upregulated in esophageal cancer samples compared with normal esophageal tissues, while USP36 expression was increased in esophageal cancer samples of all stages." (PMID 36470870, 2022). "In conclusion, we discovered a novel biological link between the Hippo/YAP axis and USP36 in esophageal carcinoma." (PMID 36470870, 2022). "We further explored the USP36 mRNA level in esophageal cancer patients." (PMID 36470870, 2022). "Considering this finding and the other oncogenic role of USP36 in previous studies, blocking USP36 could result in the synchronous inhibition of multiple oncogenic pathways to treat esophageal cancer." (PMID 36470870, 2022). "Finally, by analyzing the expression of USP36 and YAP target genes from the TCGA database, we observed that USP36 was positively correlated with a cluster of YAP target genes in esophageal cancer." (PMID 36470870, 2022). "USP36 interacts with YAP and inhibits YAP polyubiquitination and breakdown, which further promotes esophageal cancer progression." (PMID 36470870, 2022).
neuroblastoma (1 paper, 2021). Neuroblastoma (NB) is the most common solid, extracranial childhood tumor. "USP36 harbors oncogenic properties and its higher expression in neuroblastoma patients correlates with poor prognosis while its downregulation significantly reduces tumor growth in neuroblastoma cell lines and xenograft models." (PMID 35111679, 2021).
rectal cancer (1 paper, 2024). A primary or metastatic malignant neoplasm that affects the rectum. "Among the candidate USPs, USP39 and USP36 expression differed significantly, consistent with observations in patients with colon and rectal cancer." (PMID 38876304, 2024).
tumor (15 papers, 2011 to 2025). "Notably, the expression of USP36 is closely linked to the tumor microenvironment, indicating its possible clinical implications." (PMID 38785979, 2024). "Meanwhile, the development of specific inhibitors for USP36 should be accelerated to provide new strategies for precise tumor diagnosis and treatment." (PMID 40909126, 2025). "Meanwhile, the development of highly selective small-molecule inhibitors targeting USP36 will offer a more specific tool for the precise regulation of DNA replication stress and overcoming tumor chemoresistance." (PMID 40909126, 2025). "The proliferation of tumor cells is highly dependent on ribosome biogenesis, and USP36 has been proven to promote ribosome biogenesis through multiple mechanisms." (PMID 40909126, 2025). "Overall, these results indicated that ERα partially accounts for the anti-tumor effect of USP36 depletion." (PMID 39215346, 2024). "USP36 has been confirmed to play a pro-cancer role across diverse cancer types, and its knockout has demonstrated a substantial reduction in tumor development and migration." (PMID 38785979, 2024). "Multiple studies have provided evidence that USP36 promotes the proliferation and migration of tumor cells." (PMID 38785979, 2024). "In these studies, USP36 was abnormally expressed in tumor tissues and related to poor prognosis, suggesting that USP36 is an oncogene." (PMID 38876304, 2024). "The xenograft mouse model verified that silencing USP36 in MCF-7 cells suppressed tumor growth in vivo." (PMID 39215346, 2024). "The xenograft model showed that USP36 overexpression significantly promoted ESCC tumor growth in vivo." (PMID 36470870, 2022). "In the xenograft mouse model, USP36 depletion inhibited tumor growth, and this effect was reversed by YAP overexpression in KYSE150 cells." (PMID 36470870, 2022). "Western blot showed the total amount of USP36 protein was increased in tumor vs matched normal tissues of 8 ESCC patients." (PMID 36470870, 2022). "The xenograft model demonstrated that USP36 depletion significantly reduced ESCC tumor growth in vivo." (PMID 36470870, 2022). "They demonstrated that UTP14a forms a complex with USP36/Fbw7γ, stabilizes c‐Myc in the nucleolus, and inhibits c‐Myc degradation; knockdown of UTP14a leads to a decrease in c‐Myc levels and inhibits tumor growth." (PMID 31496055, 2019). "Therefore, targeting USP36 and its regulated mechanisms is expected to be a promising strategy for tumor therapy." (PMID 40909126, 2025). "Research has shown that USP36 promotes tumor progression by deubiquitinating a variety of proteins." (PMID 40909126, 2025). "Therefore, in the future, it is still necessary to deeply study the mechanism of action between USP36 and ribosome biogenesis in tumor cells and explore its potential as a new target for tumor therapy." (PMID 40909126, 2025). "AutoDock tool and ubiquitin-AMC hydrolysis assay identified cinobufotalin (CBF), an anti-tumor drug, maybe a USP36 inhibitor by inhibiting its deubiquitination activity." (PMID 38517383, 2024). "Moreover, the xenograft mouse model confirmed that overexpression of USP36 WT, compared to USP36 C131A, can increase tumor growth in vivo." (PMID 39215346, 2024). "Future studies may also include the characterization of the USP36-miRNA biogenesis pathway in tumorigenesis and tumor growth." (PMID 36950067, 2023). "Another m6A modifier, ALKBH5, is stabilized by the deubiquitinase USP36 in GSCs, stimulating tumor growth and TMZ resistance, and this USP36–ALKBH5 relationship may provide another targetable scaffold in GSCs." (PMID 37444568, 2023). "The reintroduction of ALKBH5 into the USP36-deleted GSC cells significantly mitigated the inhibitory impact observed with USP36 knockout, particularly in cell proliferation, stemness, and tumor growth of the GSC cells." (PMID 38398118, 2024).
tumor (continued). "More recently, it has been shown that USP36 enhances CHD7 protein stability by direct deubiquitination, subsequently facilitating tumor progression." (PMID 33237263, 2020). "However, how USP36 regulates ribosome biogenesis in tumor cells has not been fully studied." (PMID 40909126, 2025).